FBXO40 (F-box protein 40)
Description:
Probable substrate-recognition component of the SCF (SKP1-CUL1-F-box protein)-type E3 ubiquitin ligase complex that may function in myogenesis.
Synonyms: FBX40; KIAA1195
Tractability: PROTAC: ubiquitination databases record sites on it.
Gene: Protein-coding gene on chromosome 3 (121,592,886 to 121,630,434, forward strand). Ensembl gene ENSG00000163833.
Subcellular location: Cytoplasm
Pathways (Reactome):
Immune System: Antigen processing: Ubiquitination & Proteasome degradation
Metabolism of proteins: Neddylation
Gene Ontology:
Molecular function: ubiquitin protein ligase activity; zinc ion binding
Biological process: muscle cell differentiation; SCF-dependent proteasomal ubiquitin-dependent protein catabolic process
Cellular component: cytoplasm; cytosol; SCF ubiquitin ligase complex
Genetic constraint (gnomAD): Loss-of-function variants: 52 observed, 56.31 expected, observed/expected ratio (o/e) 0.92, 90% interval 0.74 to 1.16. The upper end of that interval is the gene's LOEUF score, 1.16, which puts it in group 5 of 6, group 1 being the genes least tolerant of losing a copy. Missense variants: 895 observed, 918.92 expected, observed/expected ratio (o/e) 0.97, 90% interval 0.92 to 1.03. Synonymous variants: 340 observed, 338.48 expected, observed/expected ratio (o/e) 1, 90% interval 0.92 to 1.1.
Homologues: Orthologues: chimpanzee FBXO40 (99% identical), macaque FBXO40 (97% identical), pig FBXO40 (89% identical), rabbit FBXO40 (88% identical), dog FBXO40 (87% identical), guinea pig FBXO40 (85% identical), rat Fbxo40 (85% identical), mouse Fbxo40 (85% identical), tropical clawed frog fbxo40 (57% identical), zebrafish fbxo40.2 (45% identical), zebrafish fbxo40.1 (44% identical), Caenorhabditis elegans C10E2.2 (16% identical). Paralogues in human: FBXO30 (33% identical).
Diseases named in the same sentence as FBXO40 in open-access papers:
FBXO40 is named in the same sentence as 15 diseases in open-access papers, as found by Europe PMC text mining. Sharing a sentence is not in itself a finding about the gene and the disease. The quoted sentences say what the papers report.
Insulin resistance (3 papers, 2021 to 2022). Increased resistance towards insulin, that is, diminished effectiveness of insulin in reducing blood glucose levels. "STAT3 induces insulin resistance in muscles by leading to degradation of IRS-1 through the upregulation of F-Box Protein 40 (Fbxo40), a muscle-specific E3 ubiquitin ligase." (PMID 35454131, 2022). "Fbxo40, a muscle-specific E3 ubiquitin ligase targeting the IRS1 for degradation, is activated by Stat3 and contributes to muscular insulin resistance." (PMID 34943061, 2021). "It is reported that the mice knockout for SCF Fbxo40 shown elevated levels of IRS1 of the insulin signaling pathway and play a vital role in insulin resistance." (PMID 33669862, 2021).
limb-girdle muscular dystrophy (2 papers, 2014 to 2021). Limb-girdle muscular dystrophy (LGMD) is a heterogeneous group of muscular dystrophies characterized by proximal weakness affecting the pelvic and shoulder girdles. "FBXO40 expression is decreased in muscles from Limb-girdle muscular dystrophy (LGMD) patients, and up-regulated in mice skeletal muscle following denervation and in chronic kidney disease (CKD) mice model, but not during starvation." (PMID 33466753, 2021). "However, in humans, FBXO40 gene expression decreases in the muscle of Limb-girdle muscular dystrophy (LGMD) patients." (PMID 24550841, 2014).
Alzheimer disease (1 paper, 2018). A progressive, neurodegenerative disease characterized by loss of function and death of nerve cells in several areas of the brain leading to loss of cognitive function such as memory and language. "Genetic variants in the FBXO40 gene were found genome-wide significant for Alzheimer's disease in the APOE e4 carriers and skin aging." (PMID 29850221, 2018). "In the present study we examined the association of two intronic variants in LUZP2 and FBXO40, previously reported genome-wide significant for the late-onset Alzheimer's disease, with the cognitive performance in a normal elderly population." (PMID 29850221, 2018).
Cerebral ischemia (1 paper, 2021). Restriction of arterial blood supply to the brain associated with insufficient oxygenation to support the metabolic requirements of the tissue. "We speculated that there was relatively little involvement of Fbxo40 in cerebral ischemia-associated hepatic and muscular insulin resistance because IRS1 content remained constant among the groups." (PMID 34943061, 2021).
dementia (1 paper, 2018). Loss of intellectual abilities interfering with an individual's social and occupational functions. "No direct functional evidence of the involvement of LUZP2 or FBXO40 proteins in neurodegenerative process in AD and dementia has been found." (PMID 29850221, 2018).
dilated cardiomyopathy (1 paper, 2020). Cardiomyopathy which is characterized by dilation and contractile dysfunction of the left and right ventricles. "Similar to the cullin-1 substrate adapter Fbxo40, hearts of mice that lack Prmt1 suffer from dilated cardiomyopathy and show aberrant Asb2 splicing." (PMID 33114658, 2020). "Cardiac specific Prmt1 knockouts develop a severe form of dilated cardiomyopathy, accompanied by a previously uncharacterized splice isoform of Fbxo40." (PMID 33114658, 2020).
endometrial cancer (1 paper, 2023). Primary or metastatic malignant neoplasm involving the endometrium (mucous membrane that lines the endometrial cavity). "In this study, FBXO40 expression levels in endometrial cancer tissues were lower than those in normal tissues, and it was found to be a risk factor for poor endometrial cancer prognosis." (PMID 36611207, 2023).
muscular dystrophy (1 paper, 2021). Muscular dystrophy (MD) refers to a group of more than 30 genetic diseases characterized by progressive weakness and degeneration of the skeletal muscles that control movement. "Upregulated in both datasets was Tbc1d12 involved in increasing glucose uptake, whereas the shared downregulated genes included Ptp4a3, the downregulation of which increases expression of ECM genes, and Fbxo40, the downregulation of which has been observed in muscular dystrophy." (PMID 34502375, 2021).
schizophrenia (1 paper, 2018). A major psychotic disorder characterized by abnormalities in the perception or expression of reality. "In summary, in the present study we observed the association with cognitive performance estimated by MoCA for genetic variants in the LUZP2 and FBXO40 genes previously linked to the AD and schizophrenia in GWA studies." (PMID 29850221, 2018).
FBXO40 also shares sentences with these, for which no sentence is quoted: Atrophy (1 paper); autism (1); Bradycardia (1); cancer (1); chronic kidney disease (1); tumor (1).